SNRNP70 (small nuclear ribonucleoprotein U1 subunit 70)
Description:
Component of the spliceosomal U1 snRNP, which is essential for recognition of the pre-mRNA 5' splice-site and the subsequent assembly of the spliceosome. SNRNP70 binds to the loop I region of U1-snRNA. [Isoform 3]: Truncated isoforms that lack the RRM domain cannot bind U1-snRNA. [Isoform 4]: Truncated isoforms that lack the RRM domain cannot bind U1-snRNA.
Synonyms: U1-70K; RNPU1Z; RPU1; SNRP70; Snp1; U170K; U1AP; U1RNP
Tractability: Small molecule: a structure with a bound ligand is known. PROTAC: UniProt records ubiquitination sites on it; ubiquitination databases record sites on it; its protein half-life has been measured.
Gene: Protein-coding gene on chromosome 19 (49,085,164 to 49,108,613, forward strand). Ensembl gene ENSG00000104852.
Subcellular location: Nucleus speckle; Nucleus, nucleoplasm
Subcellular location (Human Protein Atlas): Nucleoplasm
Pathways (Reactome):
Metabolism of RNA: mRNA Polyadenylation; mRNA Splicing - Major Pathway
Gene Ontology:
Molecular function: protein binding; RNA binding; U1 snRNA binding; mRNA binding; nucleic acid binding; U1 snRNP binding
Biological process: mRNA splicing, via spliceosome; negative regulation of chaperone-mediated autophagy; negative regulation of protein refolding; regulation of RNA splicing; spliceosomal snRNP assembly; cellular response to retinoic acid; cellular response to transforming growth factor beta stimulus; cellular response to tumor necrosis factor
Cellular component: lysosomal lumen; nuclear speck; nucleoplasm; nucleus; precatalytic spliceosome; spliceosomal complex; U1 snRNP; U2-type prespliceosome
Genetic constraint (gnomAD): Loss-of-function variants: 8 observed, 43.8 expected, observed/expected ratio (o/e) 0.18, 90% interval 0.11 to 0.33. The synonymous counts are far from expectation, so gnomAD's model fits this gene poorly and the ratio says little. Missense variants: 526 observed, 599.05 expected, observed/expected ratio (o/e) 0.88, 90% interval 0.82 to 0.94. Synonymous variants: 318 observed, 229.59 expected, observed/expected ratio (o/e) 1.39, 90% interval 1.26 to 1.52.
Homologues: Orthologues: chimpanzee SNRNP70 (100% identical), dog SNRNP70 (99% identical), guinea pig SNRNP70 (98% identical), macaque SNRNP70 (98% identical), mouse Snrnp70 (97% identical), pig SNRNP70 (97% identical), rat Snrnp70 (97% identical), rabbit SNRNP70 (85% identical), tropical clawed frog snrnp70 (80% identical), zebrafish snrnp70 (72% identical), Drosophila melanogaster snRNP-U1-70K (46% identical), Caenorhabditis elegans rnp-7 (36% identical). Paralogues in human: SNRNP35 (23% identical).
Diseases named in the same sentence as SNRNP70 in open-access papers:
SNRNP70 is named in the same sentence as 79 diseases in open-access papers, as found by Europe PMC text mining. Sharing a sentence is not in itself a finding about the gene and the disease. The quoted sentences say what the papers report.
rheumatoid arthritis (4 papers, 2013 to 2024). A chronic, systemic autoimmune disorder characterized by inflammation in the synovial membranes and articular surfaces. "While previous studies have linked SNRNP70 to diseases like myotonic dystrophy and rheumatoid arthritis, its role in oncogenesis had not been explored until now." (PMID 39704173, 2024).
Alzheimer disease (3 papers, 2019 to 2024). A progressive, neurodegenerative disease characterized by loss of function and death of nerve cells in several areas of the brain leading to loss of cognitive function such as memory and language. "Snrnp70 (small nuclear ribonucleoprotein 70) encodes a protein that is associated with the formation of amyloid-beta plaques that contribute to the development of Alzheimer’s Disease." (PMID 31722663, 2019). "SNRNP70 (also known as SNRP70, U1‐70K) is associated with mental health disorders and is a biomarker of Alzheimer's disease." (PMID 38664915, 2024).
breast carcinoma (3 papers, 2021 to 2025). "Here, we found four upregulated hub genes (RPSA, SEC61A1, ITGB1, PSMB5) and three downregulated hub genes (PSME3, SNRNP70, SRSF3) that are significantly associated with poor overall survival of breast cancer patients." (PMID 36293493, 2022). "We found that four interacting proteins of SNRPG are also upregulated in Cluster 1 of basal breast cancer patients with respect to Cluster 2: BUD13, CWC15, and SNRNP70 and ZMAT12, forming a cluster of interacting proteins enriched for the U2-type spliceosomal complex." (PMID 40867231, 2025).
hepatocellular carcinoma (3 papers, 2022 to 2024). A malignant tumor that arises from hepatocytes. "However, SNRNP70 is highly expressed in hepatocellular carcinoma (HCC), and increased expression correlates with poorer patient outcomes." (PMID 39598347, 2024).
rheumatic disease (2 papers, 2021). "Among these proteins, U1–70K (Snrnp70) is the target of self-reactive B cells and T cells in several rheumatic diseases, Ptbp1 is essential for B cell ontogeny and B cell receptor (BCR)-mediated antibody production, HnrnpL involved in the regulation of TNF α gene transcription." (PMID 35006449, 2021).
liver cancer (1 paper, 2024). An epithelial or non-epithelial malignant neoplasm that arises from the liver. "Taken together, these findings suggest that SNRNP70 may play an important role in immune escape in the liver cancer microenvironment." (PMID 38500533, 2024).
melanoma (1 paper, 2022). A malignant, usually aggressive tumor composed of atypical, neoplastic melanocytes. "We explored the effect of the most frequently mutated genes (RETSAT and SNRNP70) on the prognosis of the two ICI-treated cohorts (Allen-Melanoma and Miao-Melanoma)." (PMID 36059700, 2022).
cancer (10 papers, 2018 to 2025). A tumor composed of atypical neoplastic, often pleomorphic cells that invade other tissues. "Small nuclear ribonucleoprotein U1 subunit 70 (SNRNP70) as one of the components of the U1 small nuclear ribonucleoprotein (snRNP) is rarely reported in cancers." (PMID 38500533, 2024). "Of the many downregulated spliceosome complex proteins in cancer, we captured the interactions between SNRNP70, SRSF5, DDX17 and LUC7L3 in the largest component of the projected downregulated network." (PMID 34728699, 2021). "Given the importance of splicing in cancer, we focused on DASEs regulated by SNRNP70." (PMID 39704173, 2024). "Furthermore, the relationship between RETSAT and SNRNP70 and the prognosis of immunotherapy in patients with different cancers may be different due to tumor heterogeneity among different cancer types." (PMID 36059700, 2022). "Interestingly, the snRNPs which are the core components of the spliceosome seem to be rarely affected in cancer, while several mutations could be found in some cancer patients only at the SF3B1, U2AF1 or SNRNP70 genes." (PMID 29439487, 2018). "We observed a reduction in the LLPS of PABPN1 but not in its expression level in cancer cells and identified SNRPD2 and SNRNP70 as regulators of its phase separation." (PMID 40052530, 2025). "Similarly, there is currently no relevant report describing the prognostic effect of SNRNP70 in HCC and other cancers." (PMID 38500533, 2024).
tumor (10 papers, 2021 to 2026). "It is known that snRNP70 binds to U1 spliceosome RNA to form U1snRNP, a major component of the spliceosome, and U1snRNP is associated with tumor cell migration." (PMID 39598347, 2024). "Emerging studies indicates that signals from T cells and macrophages are linked to tumor growth and metastasis, implying that SNRNP70+ OB cells might enhance metastasis through communication with T cells and macrophages in OS." (PMID 39704173, 2024). "Recently, some studies show that SNRNP70 has a great potential in tumor treatment, while the relation between SNRNP70 and HCC is still unclear." (PMID 38500533, 2024). "In the SNRNP70 expressions between tumor and normal tissues, SNRNP70 was highly expressed in tumor tissues." (PMID 38500533, 2024). "The results showed that both the average weight and tumor volume were reduced in SNRNP70-knockdown mice compared with the siNC group." (PMID 39704173, 2024). "There are very few studies examining the relationship between SNRNP70 and tumor processes, so it is quite challenging to assess the role of this protein in malignancy." (PMID 39598347, 2024). "In this study, we placed SNRNP70 in HCC tissues for immune infiltration to explore the regulation of SNRNP70 on the tumor microenvironment." (PMID 38500533, 2024). "Metastatic cells exhibited elevated expression of SNRNP70, which was prevalent across metastatic clusters except for tumor-infiltrating lymphocytes (TILs), whereas CD55 showed low expression in all cells." (PMID 39704173, 2024). "Our results identified RBPs including PCBP2 and SNRNP70 responsible for differential ASEs upregulated in BLCA with high-level neoplasm grade." (PMID 37810965, 2023). "snRNP70 was less abundant in the perilesional region than in tumor area (p=0.0046) although OLIG2 and PTN were expressed at similar levels in the corresponding samples." (PMID 35047379, 2021). "The expression level of SNRNP70 was positively correlated with the enrichment scores of the tricarboxylic acid cycle and oxidative phosphorylation pathways, whose upregulation has been shown to promote tumor metastasis." (PMID 39704173, 2024). "Herein, we found the expressions of SNRNP70 were higher in tumor tissues and cell lines, and SNRNP70 knockdown could suppress cell proliferation in HCC." (PMID 38500533, 2024). "It was found the level of SNRNP70 was positively related to immune cells in tumor tissues." (PMID 38500533, 2024). "Additionally, SNRNP70 overexpression was confirmed in OS tumor tissues relative to adjacent non-tumor tissues in both the SRP193919 and GSE42352 datasets." (PMID 39704173, 2024). "Finally, we identified several RNA binding proteins such as PCBP2, SNRNP70, and HuR, which might contribute to splicing differences between different groups of neoplasm grade in BLCA." (PMID 37810965, 2023). "Here, only two fusions were identified as enriched in the tumor cells: the previously identified CBLC::CTC-232P5.1 fusion in 16 cells and our additionally found SNRNP70::ZIK1 in eight cells." (PMID 40086881, 2025). "Here, only 2 fusions identified as enriched in the tumor cells: the previously identified CBLC::CTC-232P5.1 fusion in 16 cells and additionally found SNRNP70::ZIK1 in 8 cells." (PMID 38464114, 2024). "Crucially, the authors showed that the knockdown of SNRNP70 inhibited the proliferation and migration of HCC tumor cells." (PMID 39598347, 2024). "Mechanistically, SNRNP70 directly interacted with CD55, modulating its alternative splicing and promoting tumor progression in OS." (PMID 39704173, 2024). "In contrast to SETMAR protein isoforms, snRNP70, OLIG2 and PTN protein levels were lower inside the necrotic area, while being detected at higher levels within the tumor region." (PMID 35047379, 2021). "While some of these proteins such as SNRNP70 and SRSF5 are the components of the spliceosome complex, the others, namely, SORBS1, TPM2 and MYH11 were reported to have a role in tumor metastasis and development 41–43." (PMID 34728699, 2021).
tumor (continued). "Finally, we identified several RBPs such as PCBP2, SNRNP70, HuR, and TIA1, which might contribute to splicing differences between different groups of neoplasm grade in BLCA." (PMID 37810965, 2023). "The results showed that ASEs up-regulated in BLCA with high-level neoplasm grade were enriched to several RBPs’ motifs, including “poly-T” motifs and polypyrimidine tract (Py-tract) sequence of HuR, CPEB4, TIA1, HNRNPC, PTBP1, RALY and ZC3H14, and motifs of PCBP2 and SNRNP70." (PMID 37810965, 2023).
neurodegenerative disease (3 papers, 2021 to 2025). A disorder of the central nervous system characterized by gradual and progressive loss of neural tissue and neurologic function. "Tau has been shown to co-aggregate with several core spliceosome components in neurodegenerative diseases, including U1-70K (SNRNP70) and U1A (SNRPA)." (PMID 41205924, 2025).
infection (1 paper, 2025). The state of being infected such as from the introduction of a foreign agent such as serum, vaccine, antigenic substance or organism. "Specifically, SNRNP40 and SNRNP70 retained the appearance of nuclear speckles following infection, while WDR12 retained a diffuse nuclear distribution." (PMID 40577456, 2025).
SNRNP70 also shares sentences with these, for which no sentence is quoted: mixed connective tissue disease (34 papers); myositis (23); systemic lupus erythematosus (23); connective tissue disease (20); systemic sclerosis (12); autoimmune disease (9); polymyositis (9); overlap syndrome (8); scleroderma (8); pulmonary arterial hypertension (6); dermatomyositis (5); inflammatory myopathies (3); interstitial lung disease (3); Sjögren's syndrome (3); Arthritis (2); Autoimmunity (2); calcinosis (2); lupus nephritis (2); pericarditis (2); pulmonary fibrosis (2); vasculopathy (2); amyotrophic lateral sclerosis (1); aseptic meningitis (1); atherosclerosis (1); breast tumor (1); cognitive decline (1); colon adenocarcinoma (1); colon cancers (1); colon mucinous adenocarcinoma (1); congenital heart block (1).
A further 38 diseases each share a sentence with SNRNP70 in 1 paper.